LINC01186 (long independently transcribed non-coding RNA 1186)
Synonyms: ZNF674-1
Gene: Long non-coding RNA gene on chromosome X (46,256,759 to 46,327,716, reverse strand). Ensembl gene ENSG00000236751.
Diseases named in the same sentence as LINC01186 in open-access papers:
LINC01186 is named in the same sentence as 4 diseases in open-access papers, as found by Europe PMC text mining. Sharing a sentence is not in itself a finding about the gene and the disease. The quoted sentences say what the papers report.
fibroids (2 papers, 2024 to 2025). "Our results showed the expression of LINC01186 was downregulated in leiomyomas." (PMID 38279317, 2024).
lung cancer (2 papers, 2019 to 2024). A malignant neoplasm involving the lung. "Recent studies also demonstrated a lower level of LINC01186 in lung cancer and papillary thyroid carcinoma (PTC)." (PMID 38279317, 2024).
LINC01186 also shares sentences with these, for which no sentence is quoted: tumor (3 papers); papillary thyroid carcinoma (1).